EGF (epidermal growth factor)
Diseases named in the same sentence as EGF in open-access papers (continued):
Sharing a sentence is not in itself a finding about the gene and the disease.
liver cancer (continued). "Agents expected to enhance the self-renewal of liver cancer stem cells, EGF/FGFβ/B27 and Il-6, induced oscillations in [Ca2+]cyt in Hep12 cells, but not in Hep-11 cells, suggesting that oscillations in [Ca2+]cyt are an important characteristic of liver cancer stem cells." (PMID 32987945, 2020). "Importantly, a total of n = 37 so far unknown disease regulated proteins were identified that can now be related to EGF induced liver cancer." (PMID 25872475, 2015). "There was elevated nuclear expression of IRS4 in liver cancer and treatment of HEPG2 cell, a liver cancer cell line with IGF-1 and EGF-induced nuclear translocation of IRS4, stimulating cell proliferation by a β-catenin/Rb/cyclin D mechanism." (PMID 37686244, 2023). "We noticed that pSmad2 transcriptionally upregulated the expression of EGF and activated PI3K/AKT signaling through EGF in liver cancer, and we confirmed this regulation relationship in CRC." (PMID 35236827, 2022). "For example, in pancreatic and liver cancers under irradiation, fibroblasts increase the secretion of various humoral factors including cytokines such as bFGF, TNF-a, VEGF, IL-6, EGF, MMP-2, and MMP-9." (PMID 35089951, 2022). "Inhibition of FUT8 can weaken hepatocyte epidermal growth factor (EGF) and hepatocyte growth factor (HGF), and thus reduce the incidence of liver cancer." (PMID 35410157, 2022). "Dysregulation of EGF, HGF, and IGF-1 plays a crucial role in the development of hepatic cancer and metastases." (PMID 34572344, 2021). "Thus, overexpression of EGF might be an important step toward development of liver cancer." (PMID 25927412, 2015). "Our previously study suggested that EGF and AREG are abundant in human liver cancer." (PMID 28541302, 2017). "EGF and EGFR were overexpressed in many cancers, such as breast, lung and liver cancer 17,20,21." (PMID 24268047, 2014). "EGF and its receptor (EGFR) may act as a bridge between inflammation and liver cancer." (PMID 40075616, 2025). "Given that EGF signaling is constitutively activated in many tumor types including in the liver of patients with HCC, EGF signaling may be an important step in liver cancer pathogenesis and that its attenuation by SCFAs may, in part, contribute to the delay in dysplasia and liver cancer." (PMID 37432606, 2023).
schizophrenia (34 papers, 2007 to 2026). A major psychotic disorder characterized by abnormalities in the perception or expression of reality. "Increased or abnormal NLRP3 and IL-1 expression along with other specific cytokines including epidermal growth factor (EGF), IL-6, and neuregulin-1 have widely been positively associated with more extreme schizophrenia-like behavior." (PMID 37139329, 2023). "EGF signaling has been associated with numerous disease processes, including schizophrenia and depression." (PMID 37881534, 2023). "Epidermal growth factor (EGF) is implicated in the pathogenesis of schizophrenia, suggesting possible value as a biomarker for disease severity or treatment response." (PMID 32194452, 2020). "The upregulation of epidermal growth factor (EGF) and/or neuregulin signaling has been implicated in the neuropathology of schizophrenia, as well as in its animal modeling." (PMID 31371697, 2019). "The functional gene mutation of EGF is found in patients with schizophrenia and/or other psychiatric diseases, but the genetic association of EGF with these illnesses is controversial." (PMID 31097747, 2019). "Neuregulin 1, first identified as a schizophrenia risk gene, is a trophic factor containing EGF (epidermal growth factor)-like domain." (PMID 31780806, 2019). "We found that neonatal exposure to EGF resulted in various behavioral deficits, most of which are implicated in schizophrenia behavioral endophenotypes." (PMID 24949465, 2014). "In 2002, DeCode Genetics Inc. reported a genetic association of the NRG1 gene with schizophrenia and our group found abnormal expression of EGF and ErbB1 in the postmortem brains of patients with schizophrenia." (PMID 24949465, 2014). "For example, genetic association studies have identified the EGF and NRG1 genes as candidates that confer risk for schizophrenia with an A61G single nucleotide polymorphism in the EGF gene associated with early disease onset in male patients." (PMID 24552586, 2014). "Epidermal growth factor (EGF) is one of the ErbB receptor ligands implicated in schizophrenia neuropathology as well as in dopaminergic development." (PMID 22022452, 2011). "The literature on the relationship between EGF and schizophrenia is sparse, but researchers indicate that EGF is associated with deficits in sensorimotor gating, latent inhibition, working memory, impaired social interaction and overall schizophrenia severity." (PMID 38004423, 2023). "Our aim is to determine whether EGF levels in peripheral blood are associated with the severity of schizophrenia symptoms and whether modulation of glutamatergic transmission has an impact on both symptomatology and EGF concentrations." (PMID 38004423, 2023). "Results of this study provide evidence that abnormal levels of EGF may be implicated in the etiology of schizophrenia, which partly supported our hypothesis." (PMID 32194452, 2020). "Collectively, these data provide further evidence that APD action via ERK may be linked to the EGF signaling system, perturbations of which have been documented in schizophrenia and suggest a remedial role for APDs such as quetiapine." (PMID 24552586, 2014). "Neuregulin-1 and epidermal growth factor (EGF) are implicated in the pathogenesis of schizophrenia." (PMID 24949465, 2014). "If EGF is involved in the mechanism of action of glutamatergic modulators (directly or indirectly), this could amend the picture of the pathomechanisms underlying schizophrenia and open new therapeutic possibilities." (PMID 38004423, 2023). "Epidermal growth factor (EGF) and its homologs, such as neuregulins, bind to ErbB (Her) receptor kinases and regulate glial differentiation and dopaminergic/GABAergic maturation in the brain and are therefore implicated in schizophrenia neuropathology involving these cell abnormalities." (PMID 36830741, 2023).
schizophrenia (continued). "The most interesting findings from this study highlight the fact that in drug-naive first episode schizophrenia patients, an association was found between EGF levels and PANSS cognitive subscale score, thus indicating that abnormal EGF levels may be a marker of cognitive deterioration." (PMID 32300175, 2020). "Serum EGF levels in patients were lower or higher than in the control group during all the stages of the illness, suggesting that dopaminergic neurons, in the case of patients, were obviously abnormal, and this abnormality is implicated in the mental symptoms and pathogenesis of schizophrenia." (PMID 32300175, 2020). "For example, neuronal HB‐EGF has been found to be upregulated in schizophrenia, and similarly seen in our Gpr143−/y mice, and in these studies of schizophrenic patients, serum EGF levels were negatively correlated with cognition in patients with schizophrenia." (PMID 41510670, 2026). "Decreased EGF serum levels have been reported in schizophrenia patients and our findings reinforce the role of EGF signalling in the disease." (PMID 40162448, 2024). "The involvement of CBLB in the EGF (Epidermal Growth Factor) pathway points to itspotential role in dopaminergic and GABAergic neuron development, which are critical in schizophrenia's neuropathology." (PMID 40162448, 2024). "This is the first randomized placebo-controlled study examining the impact of sarcosine on serum EGF concentration in schizophrenia with predominant negative symptoms." (PMID 38004423, 2023). "Transgenic mice as well as the rat/monkey models established by perinatal challenges of EGF or its homologs consistently exhibit various behavioral endophenotypes relevant to schizophrenia." (PMID 36830741, 2023). "A decreased EGF level was observed in female patients with schizophrenia (183.51 [129.66; 266.76] pg/mL) compared to male patients (158.76 [105.25; 228.23] pg/mL) (p = 0.03)." (PMID 37185739, 2023). "We found that ErbB1 receptor levels are elevated specifically in the forebrain, whereas EGF content is reduced in the blood of patients with schizophrenia." (PMID 36830741, 2023). "In contrast to EGF model rats, schizophrenia model mice established by postnatal treatment with neuregulin-1 display a variety of behavioral abnormalities depending on the neuregulin-1 splicing variants administered." (PMID 36830741, 2023). "Some studies found that the forebrains of schizophrenia patients show decreased expression of EGF in the prefrontal cortex as well as in the striatum." (PMID 37185739, 2023). "We prepared rodent models of schizophrenia by subcutaneously injecting EGF or neuregulin-1 into neonatal rats and mice." (PMID 36830741, 2023). "According to our initial postmortem findings in schizophrenia patients, ErbB1 receptors are upregulated, and EGF contents are downregulated in the forebrain regions of the patients." (PMID 36830741, 2023). "In older studies, serum EGF levels are elevated in schizophrenia, whereas more recent studies indicate a reduction in EGF levels in the first episode or in both the first episode and chronic schizophrenia." (PMID 38004423, 2023). "Male rats were challenged as neonates with either EGF or saline (EGF model vs control littermates), and the EGF-treated rats served as an animal model of schizophrenia (called EGF model rats hereafter)." (PMID 35902695, 2022). "Disruptions in epidermal growth factor (EGF) signaling and abnormalities in the processing or expression of the EGF receptors ErbB1 and ErbB2 are common in all schizophrenias." (PMID 36676048, 2022). "We prepared the animal model by administering an inflammatory cytokine, epidermal growth factor (EGF), to rat neonates, which later develop behavioral and electroencephalographic deficits relevant to schizophrenia." (PMID 35902695, 2022).
schizophrenia (continued). "In this respect, the increased self-triggered vocalizations of the present model suggest that the phenotype of EGF-treated rats is more relevant to positive symptom-like deficits of schizophrenia." (PMID 35902695, 2022). "Animal studies have demonstrated that exposure to perinatal inflammatory mediators (e.g., epidermal growth factor-EGF) induced schizophrenia-like cognitive and behavioral abnormalities after maturation." (PMID 33815179, 2021). "We measured the serum levels of EGF in 78 first-episode medication-naive schizophrenia patients, 76 medicated chronic schizophrenic patients, and 75 healthy controls using the sandwich ELISA method." (PMID 32300175, 2020). "A postmortem study of 32 individuals with schizophrenia found decreased EGF concentrations in the prefrontal cortex and striatum and elevated concentrations in prefrontal cortex compared to matched controls." (PMID 32194452, 2020). "In conclusion, schizophrenia patients have significantly lower baseline serum EGF levels than healthy controls even after obvious symptomatic improvement using antipsychotic drugs alone or drugs plus ECT." (PMID 32194452, 2020). "In this short-term preliminary clinical study, we found lower serum EGF in a cohort of schizophrenia patients compared to a healthy control group." (PMID 32194452, 2020). "The goal of this study is to compare serum EGF in schizophrenia patients before and after treatment with antipsychotics alone or combined with electroconvulsive therapy (ECT)." (PMID 32194452, 2020). "Several clinical studies have also examined alterations of serum EGF in schizophrenia patients but have yielded discrepant results." (PMID 32194452, 2020). "Serum EGF concentration is low in schizophrenia but is unchanged following treatment with antipsychotics alone or combined with ECT, regardless of clinical response." (PMID 32194452, 2020). "Low basal serum EGF suggests dysregulation of neuroprotective and inflammatory responses in schizophrenia." (PMID 32194452, 2020). "Blood levels of EGF were reduced in both medicated and drug-naive patients with schizophrenia compared to control subjects." (PMID 32300175, 2020). "Serum EGF levels showed a significant decrease in schizophrenia patients in comparison to healthy subjects." (PMID 32300175, 2020). "If the EGF-treated rats can be an animal model of schizophrenia, this result appears contradictory to ours." (PMID 31097747, 2019). "The expression of EGF, neuregulins, or ErbB receptors is reported to increase in the brain of patients with schizophrenia as well as in the blood of the patients." (PMID 31371697, 2019). "Further studies should elucidate the pathogenesis of the MMN abnormality in EGF-treated animals to verify its relevancy to schizophrenia." (PMID 31097747, 2019). "Results suggest that animals exposed to EGF during a perinatal period serve as a promising neurodevelopmental model of schizophrenia." (PMID 31097747, 2019). "Clozapine, an atypical antipsychotic drug that treated schizophrenia by blocking the EGF/ErbBs systems, has been reported to inhibit the U87MG human glioblastoma cells proliferation." (PMID 30233327, 2018). "A consistent increase in L1 copy number was also observed in the PFC tissue of two established schizophrenia animal models (i.e. maternal immune activation induced by polyinosinic : polycytidylic acid (PolyI : C) and epidermal growth factor (EGF))." (PMID 30021882, 2018). "To test the contribution of these neurotrophic factors to the neurodevelopmental abnormality of schizophrenia, we subcutaneously administered the EGF protein into rats and mice at various developmental stages, neonate, juveniles, and young adults." (PMID 24949465, 2014). "Genetic studies suggest that the genomic mutation or polymorphism for EGF, NRG1 and their receptors (ErbBs) is associated with schizophrenia risk." (PMID 22022452, 2011).
schizophrenia (continued). "Here, we prepared the animal model for schizophrenia by subcutaneously injecting EGF to newborn rats and studied the mechanism for their PPI abnormality." (PMID 22022452, 2011). "For instance, age effects do not appear to modify substantially the highly significant associations found for BDNF, RANTES, EGF, TIMP-1, ENA-78 and MDC levels with schizophrenia." (PMID 20161799, 2010). "For some protein analytes, the observed change is clearly more marked in one of the disease groups, such as in the case of BDNF and EGF for schizophrenia and insulin for depression." (PMID 20161799, 2010). "Some studies have indicated a potential link between impaired EGF signaling and the pathogenesis of schizophrenia." (PMID 19829704, 2009). "Additionally, the potential of S100A8, S100A9 and EGF as biomarkersfor disease severity and treatment response opens new possibilities for personalized therapeutic approaches in managing schizophrenia." (PMID 40162448, 2024). "In the following chapters, we summarize the dopaminergic role in the behavioral impairment of the EGF model and discuss the neuropathological implication of this model in the dopamine hypothesis for schizophrenia." (PMID 36830741, 2023). "In schizophrenia, GlyT1 blockade on GABAergic neurons prevents glutamatergic excitotoxicity, i.e., sarcosine can block neuronal and glial damage/dysfunction, which can also prevent EGF decline." (PMID 38004423, 2023). "Moreover, serum EGF levels in patients with first-episode schizophrenia were independently correlated with cognitive function (beta = −0.459, P = 0.001)." (PMID 32300175, 2020). "Furthermore, we found that serum EGF levels were related to the PANSS general psychopathology subscore of schizophrenia patients." (PMID 32300175, 2020). "Furthermore, there is a need to carry out a cohort investigation the relationship between EGF and cognitive function assessed by a battery of cognitive tests covering aspects of memory, executive function and attention in patients with schizophrenia." (PMID 32300175, 2020). "Based on a growing body of literature examining the role of neurotrophic molecules in the pathophysiology of schizophrenia, we hypothesized that serum EGF levels were significantly diminished in patients with schizophrenia compared with healthy subjects." (PMID 32300175, 2020). "Until recently, there has been no reliable evidence to indicate that peripheral EGF is implicated in the cognitive functioning of schizophrenia patients." (PMID 32300175, 2020). "In order to investigate the neurobiological roles of EGF/ErbB1 signals in schizophrenia-related behavioral phenotypes, we attempted to develop an animal model for schizophrenia using various approaches like neonatal injection, intraventricular administration and genetic overexpression of EGF3,13,14." (PMID 31097747, 2019). "In the present study, we recorded the MMN-like potential in one of the putative animal models for schizophrenia, which was perinatally EGF-treated rats, and characterized their deficits in MMN-like potential to evaluate validity of this model for schizophrenia." (PMID 31097747, 2019). "Subsequently, a Finland group reported a genetic association between the EGF gene and schizophrenia, although this has not been replicated in all ethnic populations examined." (PMID 24949465, 2014). "This cytokine-driven dopaminergic dysfunction might illustrate some of the psychopathological features of schizophrenia, although it is possible that the responsible factor(s) might be other cytokines other than EGF, NRG1, or virokine." (PMID 24949465, 2014). "Indeed, these human studies were the impetus for our research on animal modeling of schizophrenia using EGF and NRG1." (PMID 24949465, 2014). "Thus given that several studies argue for EGF system disturbance in schizophrenia, the current findings indicate a possible corrective role for APDs such as quetiapine." (PMID 24552586, 2014).